MPO (myeloperoxidase)
Diseases named in the same sentence as MPO in open-access papers (continued):
Sharing a sentence is not in itself a finding about the gene and the disease.
infection (continued). "Because iNOS mRNA in contrast to gp91phox and MPO mRNA was strongly induced after infection or LPS-stimulation, nitrite accumulation as a marker for iNOS activity was measured in the supernatants." (PMID 28697801, 2017). "Thirty days post infection, chitosan treatment resulted in MPO, MCP-1, TNF-α, IL-12p70 and IL-4 levels falling to control values, but IL-6, IL-10 and TGF-β were elevated." (PMID 29156562, 2017). "In this context, infection in the presence of fragments reduces the production of IL-8 and MPO, inflammatory immune mediators, acting to further decrease an unwanted and potentially harmful influx and activation of neutrophils at the infection site." (PMID 28373877, 2017). "Equal neutrophil degranulation was confirmed by lung myeloperoxidase levels in control and antibiotic treated mice after infection with B. pseudomallei." (PMID 28422970, 2017). "SKNO-1 cells, infected with NS, miR-15 or miR-29b-1, were analyzed for MPO activity 3-days post-infection." (PMID 28611288, 2017). "On the other hand, there was a large impairment in the ability of Myd88-/- mice to recruit neutrophils to the skin, as they demonstrated an approximately 70% reduction in myeloperoxidase levels 8 hours after infection." (PMID 28704551, 2017). "Noticeably, similar levels of neutrophil influx were observed in infection-experienced and co-immunized mice but higher MPO activity appeared to be induced in infection-experienced mice." (PMID 28030629, 2016). "The apparent neutrophil presence in mutant infected glands was still high 4 days after infection, with MPO activity ranging from 8 to 21 Units/g of gland." (PMID 27855187, 2016). "This context-dependent regulation (in absence vs in presence of infection) indicates that the preconditioning by GLs acts at a level other than the effector/mediator molecules MPO and IL17A (e.g. at the level of sensors or adaptors)." (PMID 27164990, 2016). "Previously we have shown that the deletion of serglycin affected the levels of NE in naïve mice, whereas MPO levels were unaffected, and that early neutrophil recruitment was delayed in the SG−/− mice during infection with T. gondii." (PMID 27267469, 2016). "MPO was the mediator of greatest significance, with higher concentrations in patients with infection, and CSF MPO concentration was strongly correlated with CSF neutrophil count." (PMID 26808276, 2016). "Although no serotype-specific differences in pulmonary H2O2 levels during secondary infections were observed, secondary infection with serotype 4 (followed by serotype 3) resulted in the highest MPO activity and the greatest NETs induction." (PMID 27034012, 2016). "In response to pathogens infection, the process of NETs formation has been accompanied by the concentration of several antibacterial proteins and granule proteins, including histones, MPO, NE, and cathelicidin at the site of infection." (PMID 27843440, 2016). "In contrast, secondary infection with serotype 4 revealed the highest MPO activity (∼5 to 10-fold higher than secondary infection with serotype 19F), congruent with its histopathologic severity." (PMID 27034012, 2016). "To assess this we measured myeloperoxidase activity which is a marker of neutrophil activation and accumulation in tissues during inflammation as a result of infection." (PMID 25706529, 2015). "Peak MPO activity was observed at similar kinetics post infection, suggesting rapid activation of extravasated dermal neutrophils." (PMID 26020515, 2015). "The MPO activity was only marginally increased post-infection (12% increase) and normalized to control level after vaccination in GPxtg mice." (PMID 26075398, 2015). "The pluripotency of MPO and elastase distinguishes them as unique factors controlling many aspects of infection and inflammation." (PMID 26109900, 2014). "A significant reduction (p < 0.05) in MPO activity (as compared to group 1) was seen in group 3 on all post-infection days." (PMID 25112504, 2014).
infection (continued). "At 2 hours after infection, myeloperoxidase activity was increased 1.7-fold for euglycemic rats compared with diabetic rats (P = 0.04) and free DNA was increased by 1.6-fold for euglycemic rats compared with diabetic rats (P = 0.03)." (PMID 25610878, 2014). "We observed that MPO levels increased more in WT than in Mif−/− mice during the course of infection." (PMID 25255103, 2014). "MPO IHC demonstrated that EtOH-treated animal experienced earlier and higher recruitment of neutrophils to the lungs post-infection than the untreated-Ab-infected group." (PMID 24752133, 2014). "Mice treated with EtOH (P<0.001) or untreated (P<0.001) resulted in significantly higher levels of MPO after Ab infection than did untreated neutrophils." (PMID 24752133, 2014). "Infection with P. brasiliensis yeasts resulted in increased myeloperoxidase (MPO) activity in WT and 5-LO−/− mice 24 h after intratracheal inoculation when compared with uninfected mice." (PMID 23991239, 2013). "Causal relationship has been suggested in the combination of MPO-ANCA-GN and MN in some cases, however, we should consider all the possibilities including malignancy, drug or infection associated MN as well as idiopathic MN." (PMID 23537120, 2013). "We examined colonic neutrophil and macrophage cell infiltration and found that ω-6 PUFA rich diets increased infiltration of F4/80+ macrophages and MPO+ neutrophils compared to the low ω-6 PUFA group during infection." (PMID 23405155, 2013). "As expected, the increase in myeloperoxidase activity apparent during the response to infection was reversed when neutrophils were depleted." (PMID 23935487, 2013). "Upon infection, in the immunosuppressed animals, Panobacumab induced a reduced neutrophil recruitment, as determined by MPO measurement, as a surrogate marker of neutrophil recruitment, in the lungs." (PMID 24023870, 2013). "The levels of myeloperoxidase (as neutrophil marker), TNFα, INFγ, GM-CSF, IL-1β and IL-6 transiently increased in lungs after infection, while levels of IL-10, IL-17A and IL-22 were indistinguishable from PBS controls." (PMID 22319619, 2012). "In agreement with reduced neutrophil numbers, MPO levels remained low in Ifnar1−/− kidneys at day 7 post infection." (PMID 22911155, 2012). "Regarding innate immunity, these compounds are created via myeloperoxidase at the sites of infection – as a mixture of different chloramines, from which NCT is a major component." (PMID 23139739, 2012). "Because of the lower chemokine levels (MIP-2 and KC), we investigated PMN recruitment to the infection site using a MPO assay." (PMID 22844481, 2012). "When subjected to similar intravitreal challenge with B. cereus, eyes of TNFα-/- mice had significantly less MPO and proinflammatory cytokines during the course of infection compared to that of eyes of wild type mice." (PMID 22163046, 2011). "MPO system plays an important role in the microbicidal activity of neutrophils in the innate immune response to infection." (PMID 21906393, 2011). "In this study, nanoconjugated vancomycin inhibited the myeloperoxidase activity which was increased due to VRSA infection, suggesting a protective role of nanoconjugated vancomycin." (PMID 21785683, 2011). "Our current study is consistent with these reports in that, despite similar neutrophil infiltration at the site of infection, neutrophils from preterm lambs had significantly lower myeloperoxidase levels than full-term lambs following RSV infection." (PMID 21827668, 2011). "Although infection induced significant neutrophil recruitment into the lungs of preterm lambs, neutrophils produced less myeloperoxidase than those of full-term lambs, suggesting decreased functional activation." (PMID 21827668, 2011).
infection (continued). "Vaccination with TcVac1resulted in a suppression of phagocytes’ response to challenge infection aswas evidenced by decreased activation of MPO and iNOS activity invaccinated/infected dogs as compared to that noted in non-vaccinated/acutelyinfected dogs." (PMID 21625470, 2011). "We quantified the host response by measuring neutrophil accumulation at the infection site with the myeloperoxidase (MPO) assay." (PMID 20949105, 2010). "We found substantial accumulation of neutrophils in BALF and in lung tissue, asassessed by myeloperoxidase (MPO) activity and histology, following infection." (PMID 21079759, 2010). "Glutathione depletion aggravated ileal inflammation after infection as indicated by increased levels of mucosal myeloperoxidase and interleukin-1β." (PMID 19374741, 2009). "HAdV-D53 infection induced significantly higher levels of MPO when compared to HAdV-D22 and mock infected corneas." (PMID 19492050, 2009). "We next assessed corneal myeloperoxidase (MPO) levels after infection as a measure of the presence of infiltrating neutrophils and monocytes." (PMID 19492050, 2009). "Both adult and aged mice produced similar levels of MPO, except for day 9 post-infection, in which aged mice had a significantly higher level of MPO (data not shown)." (PMID 19922665, 2009). "MPO levels and therefore accumulating neutrophils were significantly lower upon infection with B. anthracis Sterne compared to the ΔLF/EF mutant strain." (PMID 18698416, 2008). "However, seven days after infection, Poldip2 knockdown reduced viral load, decreased infiltration of myeloperoxidase (MPO)-positive neutrophils into inflamed lungs, and reduced tissue damage." (PMID 42054341, 2026). "The observed effects of Shigella infection on EE fecal biomarkers during the initial month of infection were consistent with prior research: MPO concentrations were elevated at time of infection and there was not a clear difference in NEO and AAT concentrations compared to those not infected." (PMID 40440324, 2025). "Our findings may offer epidemiological evidence to support the inflammation–infection interaction hypothesis and lay the groundwork for developing MPO-based predictive tools and individualized prevention strategies for H. pylori infection." (PMID 40943779, 2025). "Interestingly, the expression levels of CitH3, NE, MPO, PR3, and PAD4 in IDO1-KO mice after infection were lower than those in WT mice; the same was true for the levels of free DNA and MPO–DNA complexes." (PMID 40597301, 2025). "However, at 14 days post-infection, the percentage area stained for MPO was significantly higher in WT mice compared to Csf2 KO mice." (PMID 41190069, 2025). "Dectin-1 deficiency and antifungal drug treatment (Abx + AF) achieved the same effect on survival rate, blood bacterial load, lung tissue injury score, inflammatory factor levels, and mean fluorescence intensity of MPO in Abx-treated mice after intranasal infection with K. pneumoniae." (PMID 40817809, 2025). "Although the pathogenic MPO variants are not necessarily the root cause of the patient’s susceptibility to infection, her case is illustrative of how seizures can be a consequence of an indirect pathway involving non-nervous body systems." (PMID 39825393, 2025). "Persistently elevated serum NET markers (NE, MPO, cfDNA) for ≥6 months post-infection." (PMID 41262872, 2025). "Analogous to the function of recognized tryptophan-metabolizing enzymes such as indolamine 2,3-dioxygenase, tryptophan oxidation by MPO may play a signaling role during infection and inflammation." (PMID 40081572, 2025). "Furthermore, infection significantly reduced the percentage of neutrophils expressing the key antimicrobial enzymes MPO (from 85.3 to 22.4%) and NOX2 (from 94.9 to 55.0%)." (PMID 41334168, 2025). "As expected, at 6 hours post-infection with K. pneumoniae, lung MPO levels drastically increased." (PMID 40034692, 2025).
infection (continued). "Significant elevations of MPO, NE, and Cit-H3 in Delta-infected cats, as demonstrated by both western blot and qRT-PCR analyses, underscores the heightened neutrophil activation in response to Delta infection." (PMID 40475786, 2025). "Similarly, the expression of CXCR2, PSGL-1, and MPO in neutrophils in the air pouch in the MRSA + Lanata group increased significantly at 6 h post-infection and were lower than those in the MRSA group at 12 h." (PMID 39877391, 2024). "Although MPO is considered a critical protein for innate immunity, intriguingly, its depletion does not seem to increase the susceptibility to infections unless superimposed with poorly controlled diabetes mellitus." (PMID 39199135, 2024). "By day 2 post-infection, both IL-8 and MPO were readily detectable in the urine of challenged macaques with a peak observed at day 7 and concentrations progressively decreasing at subsequent timepoints before reaching baseline levels at day 28 post-infection." (PMID 39297649, 2024). "The bioactivity of the fractions was evaluated for the first time, for reduction of infection, myeloperoxidase (MPO) as a marker of infection; neutrophil infiltration or resolution; kinetics of inflammatory cytokines; and wound repair kinetics (viz., nitrite levels and iNoS expression)." (PMID 38373996, 2024). "Together, these data indicate that neither H. haemolyticus nor rHpl exposures elevated lung immunopathology compared with NTHi infection alone, and instead, some responses including lung MPO and barrier permeability (as measured by albumin levels) were reduced." (PMID 38380941, 2024). "It should be noted that MPO does not appear to be an essential or critical enzyme in human physiology, and its depletion does not seem to increase the susceptibility to infections." (PMID 39199135, 2024). "In this study, the peak bacteriuric period (days 5–15 post-infection) was associated with a visible increase of PMN cells in urine sediments and higher levels of neutrophil-associated inflammatory biomarkers IL-8 and MPO in urine compared with uninfected sentinels." (PMID 39297649, 2024). "The results of this experimental study showed that NE infection exerted long-term effects on broiler chickens, including reduced intestinal barrier function 7 d after infection, continued high levels of MPO and CRP in the serum, and inferior growth performance compared to those in the NC group." (PMID 37143114, 2023). "MPO deficiency has no established clinical phenotype but reports indicate increased susceptibility to infection and chronic inflammation." (PMID 37954595, 2023). "In addition, MPO showed significant positive correlations with Resistin and IL-6 in fatal infection." (PMID 37598150, 2023). "The myeloperoxidase (MPO) enzyme acts on H2O2 generated in injured tissues through the respiratory burst, with evidence that humans harboring MPO mutations show increased susceptibility to infections." (PMID 37047441, 2023). "However, in contrast to NADPH oxidase, MPO has a limited function in controlling infection in either humans or mice." (PMID 38037141, 2023). "The inappropriate activation of Tolllike receptors involved in the anti-microbial immune response at a time of neutrophil activity increasing the local presence of MPO provides a potential pathophysiological linkage to explain the clinical links between infection and AAV." (PMID 36674855, 2023). "In addition to cytokine measurements, a tissue MPO assay revealed a significant increase in MPO levels in the infection group." (PMID 37781285, 2023). "MPO can modify C3, leading to its activation and the release of C3 fragments, which in turn can trigger inflammatory responses and attract immune cells to the site of infection." (PMID 37999488, 2023).
infection (continued). "Meanwhile, lessening NO along with LYZ and MPO levels at the 1st and 3rd week post-infection in groups supplemented with various levels of eugenol nanoemulsion, with more pronounced effects for the high dose, revealed its potential role in alleviating the harmful effects of bacteria." (PMID 35812892, 2022). "For these experiments, we raised the infection dose to 5 × 105 yeast particles per animal in order to facilitate the detection of a survival benefit against untreated WT mice that are more resistant to infection than MPO knockout animals." (PMID 35945238, 2022). "On the other hand, a smaller amount or lack of MPO can also cause an increase in oxygen metabolism and, therefore, a higher-than-normal production of ROS, leading to a greater susceptibility to infection and increased risk of cancer in humans." (PMID 36259798, 2022). "Interestingly, frequencies of MPO+ neutrophils significantly decreased between day 25 and day 35 post infection but further decreased upon ABAH treatment when compared to the vehicle-treated group." (PMID 35269694, 2022). "Through this work, it was possible to confirm the inhibitory capacities on the myeloperoxidase enzyme, which can be an excellent tool to prevent the progression of inflammation or infection to more severe conditions, allowing it to act quickly and at an early stage in these processes." (PMID 35335191, 2022). "However, at 3 days post-infection, control animals contained a large fraction of neutrophils that exhibited high MPO but low Ly6G expression." (PMID 35945238, 2022). "Thus, taken with the significant decrease in MPO concentration, the reduction in albumin concentration for particle-treated mice suggests significant attenuation of lung injury during infection." (PMID 35737459, 2022). "The device can be used qualitatively (the user can give a yes or no diagnosis) and quantitatively (the colorimetric readout can be quantified using an office desktop scanner), and the produced color intensity can be correlated to infection-related MPO activities." (PMID 36012396, 2022). "While both Ly6CHi and Ly6CLo blood monocytes have demonstrated similar phagocytic capacity, only the Ly6CHi subset expressed high levels of CCR2 and CD62L and are thus theorized to play an inflammatory role when they are recruited to sites of infection, which is consistent with MPO expression." (PMID 35897821, 2022). "Upon infection with the non-encapsulated Spneu strain, neutrophil influx into the lung was not significantly impaired in myeloid Lkb1-deficient mice, and MPO levels in BALF were comparable to control mice." (PMID 36096803, 2022). "At 12 h post infection, the kidneys of both MPO-deficient and Clo-L-treated mice were colonized in a non-selective manner, whereas in the spleens of infected MPO-deficient animals, C. albicans colonized predominately the marginal zone (MZ)." (PMID 35945238, 2022). "This work also supports the pharmacological use of these species that inhibit MPO, and exhibit activity that may be related to the treatment of infection and inflammation." (PMID 35335191, 2022). "The paradigm of MPO release from activated neutrophils is normally related to rectifying disease states and combating different types of microbial activities at the sites of infection." (PMID 34080136, 2021). "Augmented infections for both wild-type and MPO-/- mice had significantly more liver bacterial numbers and increased weight loss than respective non-augmented infections." (PMID 34529737, 2021). "Importantly, and consistent with the proteomic analysis, significant increases in neutrophil elastase, myeloperoxidase, and catalase were observed on days 2 and 4 after infection, peaking on day 6 relative to controls." (PMID 34319784, 2021). "Therefore, strategies are needed to ameliorate the metabolic and mineral disorders in addition to preventing relapse and infection to improve MPO-AAV prognosis." (PMID 33481903, 2021).